FGFR4 (fibroblast growth factor receptor 4)
Diseases named in the same sentence as FGFR4 in open-access papers (continued):
Sharing a sentence is not in itself a finding about the gene and the disease.
hepatocellular carcinoma (continued). "There is growing evidence that the FGFR4 pathway may contribute to the development of hepatocellular carcinoma (HCC), and selective FGFR4 inhibitors have shown remarkable anti-tumor activity in HCC xenografts harboring FGF19-overexpression." (PMID 28445152, 2017). "However, the association between FGFR4 genetic variants and the risk of hepatocellular carcinoma (HCC) has not yet been determined." (PMID 25860955, 2015). "FGFR4 is a driver of some solid tumors, for example, rhabdomyosarcoma (RMS) and hepatocellular carcinoma (HCC), and hence has attracted efforts to seek highly selective inhibitors." (PMID 39287197, 2025). "Though FGFR4 is the major FGFR present in mature hepatocytes, elevated expression of FGFR1 has been observed in hepatocellular carcinoma (HCC) and contributed to tumor development." (PMID 36263162, 2022). "A subtype of hepatocellular carcinoma (HCC) expresses FGF19, which activates the FGFR4 signaling pathway that induces cell proliferation." (PMID 33794926, 2021). "In another study, the interaction of FGFR4 with the βKlotho (KLB) co-receptor, a metabolic regulator that is frequently disrupted in hepatic cancers, was shown to inhibit cell proliferation and induce caspase-3-dependent apoptosis in hepatomas by decreasing AKT and mTOR activity." (PMID 34830951, 2021). "We hypothesized that the constitutive activation of FGFR4 in MDA-MB-468 and HCC1937 could be mediated by an autocrine secretion of FGF19 as has been shown in other cancers, such as hepatocellular carcinomas, lung squamous cell carcinomas, and colon adenocarcinomas." (PMID 27192118, 2016). "Furthermore, up-regulation of fibroblast growth factor receptor 4 (FGFR4) levels, a target for new small molecule inhibitors for the treatment of hepatocellular carcinoma, may also compensate the inhibition of proliferation." (PMID 27443843, 2016). "A study showed that miR-486-3p can adjust the sorafenib response in hepatocellular carcinoma (HCC), targeting both fibroblast growth factor receptor 4 (FGFR4) and epidermal growth factor (EGFR), and adjusts it to be a better treatment target than FGFR4 and EGFR inhibitors." (PMID 35215154, 2022).
rhabdomyosarcoma (45 papers, 2010 to 2025). A rare aggressive malignant mesenchymal neoplasm arising from skeletal muscle. "Recent advances in the molecular pathophysiology of rhabdomyosarcomas have highlighted genetic events that correlate with tumor behavior, chemoresistance, and thus outcome, including FGFR4 mutations and RAB3IP-HMGA2 fusion transcript expression." (PMID 40094002, 2025). "Among participants achieving CR, all received combination therapy (mTOR inhibitor with chemotherapy in rhabdomyosarcoma with PI3K or FGFR4 gain-of-function mutations; irinotecan combination therapy in neuroblastoma with an ATRX mutation)." (PMID 38755180, 2024). "Though caused by multiple distinct genetic drivers, the subtype in which FGFR4 has been most often implicated is fusion-positive rhabdomyosarcoma." (PMID 39576839, 2024). "In recent years, FGFR4 has been implicated as a potential therapeutic target in rhabdomyosarcoma (RMS), a pediatric soft tissue sarcoma." (PMID 39576839, 2024). "Amplification or mutation of FGFR4 is rarely perceived as an oncogene except in rhabdomyosarcoma (7.5%)." (PMID 35494629, 2022). "The PAX3‐FOXO1 fusion protein in high‐risk rhabdomyosarcomas increases FGFR4, FGFR2, and FGF7 levels." (PMID 34850536, 2022). "In contrast, nonsynonymous mutations of FGFR4 are relatively rare, although a mutation in the tyrosine kinase domain (V550L) was reported in rhabdomyosarcoma." (PMID 34272467, 2021). "Mutations in the kinase domain of FGFR1 and FGFR4 occur in gliomas and rhabdomyosarcomas, respectively." (PMID 34272467, 2021). "The kinase domain mutations of FGFR4 (V550E/L and N535D/K) were described in 7% of rhabdomyosarcoma, leading to tumour growth in vivo and drug resistance to all type I and some type II inhibitors in patients." (PMID 33655556, 2021). "FGFR4 has been implicated in other pediatric malignancies such as rhabdomyosarcoma as well as adult cancers." (PMID 32703985, 2020). "Two point mutations in the TK domains of the FGFR4 gene, K535 and E550, have been identified in rhabdomyosarcoma." (PMID 30634399, 2019). "Amplification and activating mutations in FGFR4 have been identified in 7-8% of rhabdomyosarcoma patients and FGFR inhibitors are potentially effective in a rhabdomyosarcoma mouse model expressing mutated FGFR4." (PMID 28030802, 2017). "Our previous report showed over expression of FGFR4 in rhabdomyosarcoma, and furthermore, activating mutation of FGFR4 can promote metastasis in human rhabdomyosarcomas." (PMID 27154171, 2016). "Some mutations in the FGFR4 kinase domain (N535K and V550E) lead to sustained activation of the FGFR4 signaling pathway in rhabdomyosarcoma, malignant lung adenoma and glioma." (PMID 27618313, 2016). "Additionally, overexpression of FGFR4 is associated with advanced stage cancer and poor survival in rhabdomyosarcoma (RMS)." (PMID 26993773, 2016). "Given our findings, we believe that targeting FGFR4 will be most effective in ERMS with high expression (due to amplification) or mutation of FGFR4 or in alveolar rhabdomyosarcoma (ARMS) where the PAX3/7-FOXO1 fusion gene found in ARMS directly increases expression of FGFR4." (PMID 24124571, 2013). "In contrast, FGFR4 in rhabdomyosarcoma showed activating mutations in 7.5% of patients." (PMID 23696849, 2013). "Moreover, FGFR4 expression levels were associated with metastatic disease and poor survival in gastric, lung, breast adenocarcinoma and rhabdomyosarcoma." (PMID 23696849, 2013). "This strategy has been explored in the preclinical models of solid tumors like glioblastoma (HER2 and IL13Rα2 CARs) and rhabdomyosarcoma (FGFR4 and B7-H3 CARs) and shown to result in superior durability of anti-tumor effects." (PMID 40808942, 2025). "Beyond rhabdomyosarcoma, FGFR4 has also garnered attention in recent decades for its dysregulation in other adult and pediatric cancers." (PMID 39576839, 2024).
rhabdomyosarcoma (continued). "This knockout model can also be utilized in existing zebrafish disease models to thoroughly understand the role of FGFR4 in various diseases, including rhabdomyosarcoma and other cancers." (PMID 39576839, 2024). "Fibroblast growth factor receptor 4 (FGFR4) is known to contribute to rhabdomyosarcoma progression; here, we sought to investigate the involvement and potential for therapeutic targeting of other FGFRs in this disease." (PMID 34850536, 2022). "To investigate strategies to inhibit FGFR4-dependent rhabdomyosarcoma growth we searched for a model cell line suitable for this purpose." (PMID 36097178, 2022). "Rhabdomyosarcoma (RMS) is a paediatric cancer driven either by fusion proteins (e.g., PAX3-FOXO1) or by mutations in key signalling molecules (e.g., RAS or FGFR4)." (PMID 36097178, 2022). "The fibroblast growth factor receptor 4 (FGFR4) alterations play an essential role in developing cancer in the breast, ovarian, prostate, colon, rhabdomyosarcoma, pancreatic, and gastric, hepatocellular, and pituitary adenocarcinomas." (PMID 34026732, 2021). "Three embryonal rhabdomyosarcomas harboured alterations in FGFR4 whilst the two aggressive fibromatosis and an embryonal RMS had CTNNB1 mutations." (PMID 33916788, 2021). "FGFR4 was previously recognized as an upstream signaling pathway that activates BCL2L1 to combat apoptosis in rhabdomyosarcoma." (PMID 34351305, 2021). "In Rhabdomyosarcoma, FGFR4-specific single-domain antibodies demonstrated a good specificity and affinity for targeting FGFR4-expressing cells and for blocking the FGF19–FGFR4–MAPK signaling axis." (PMID 34683129, 2021). "GAs in FGFR4 have been described in 6.1% of rhabdomyosarcomas (RMS) overall, but is enriched (9.6% in the PAX gene fusion negative subset (generally embryonal subtype)." (PMID 32393201, 2020). "The fibroblast growth factor receptor 4 (FGFR4) is overexpressed in rhabdomyosarcoma (RMS) and represents a promising target for treatments based on specific and efficient antibodies." (PMID 33182650, 2020). "Omipalisib potently inhibits FGFR4-V550E tumor-derived cell and human rhabdomyosarcoma cell viability and reduces the growth of rhabdomyosarcoma in vivo." (PMID 31277692, 2019). "We have identified mutation in FGFR4, which acts as an oncogene, and suggested therapeutic targeting of FGFR4 in rhabdomyosarcomas." (PMID 27154171, 2016). "FGFR4 has been reported to be over-expressed in human breast, prostate, colon, rhabdomyosarcoma, gastric, pancreatic, hepatocellular and pituitary adenocarcinomas, where it can contribute to tumor progression by multiple mechanisms." (PMID 23696849, 2013). "Our group had previously identified FGFR4 as a target in rhabdomyosarcoma using gene expression array analysis and we have demonstrated FGFR4 activity in disease." (PMID 23251904, 2012). "For example, FGFR4, the level-1 gene highly expressed in rhabdomyosarcomas (RMS) class, is ranked within the top 10 level-1 genes in the SRBCT data set." (PMID 21909426, 2011). "Though broadly regarded as a therapeutic target of interest, a mechanistic understanding of the role of FGFR4 in rhabdomyosarcoma and other cancers remains unclear." (PMID 39576839, 2024). "In addition, CAR T-cell therapy targeting FGFR4 in rhabdomyosarcoma is in preclinical development stages and has had success in mouse allograft models to decrease tumor burden." (PMID 39576839, 2024). "FGFR4 is a receptor tyrosine kinase overexpressed in rhabdomyosarcoma (RMS) and mutationally activated in ~10% of fusion-negative (FN) cases." (PMID 37627061, 2023). "In rhabdomyosarcoma, FGFR4 promotes both metastasis and therapeutic resistance." (PMID 36831514, 2023).
rhabdomyosarcoma (continued). "Amplification in FGFR4 occurs in cell lines of rhabdomyosarcoma, prostate and liver cancers." (PMID 33655556, 2021). "Additionally, highly FGFR4 expression was detected in rhabdomyosarcoma." (PMID 30634399, 2019). "Together, these findings highlight the therapeutic relevance of FGFR4 and FGFR2 signaling in fusion-driven rhabdomyosarcoma and support the further development of FGFR-targeted approaches in this malignancy." (PMID 40508013, 2025). "FGFR4–CAR–iCasp9 model has specifically and effectively targeted rhabdomyosarcoma (RMS) cells expressing high levels of FGFR4." (PMID 39625520, 2024). "In the future, we plan to use these knockout zebrafish to understand the genetic cooperation between FGFR4 and PAX3::FOXO1, the predominant driver of fusion-positive rhabdomyosarcoma." (PMID 39576839, 2024). "In fusion‐positive rhabdomyosarcoma (FP‐RMS), high levels of FGFR4 expression are transcriptionally driven by the protein product of the recurrent fusion gene PAX3‐FOXO1." (PMID 34850536, 2022). "We also included the rhabdomyosarcoma cell line, RH30, expressing wild-type FGFR4 in these experiments." (PMID 36097178, 2022). "In particular, alterations in fibroblast growth factor receptor 4 (FGFR4) occur in breast, ovarian, prostate, colon, rhabdomyosarcoma, pancreatic, gastric, hepatocellular and pituitary adenocarcinomas." (PMID 28376106, 2017). "In rhabdomyosarcoma tumors without PAX3-FOXO1 gene fusions, FGFR4 mutations are found in 10% of cases, while nearly all tumors have elevated FGFR4 expression." (PMID 40510032, 2025). "By contrast, FGFR4 is over-expressed in basal-like breast, liver, colon, head and neck and prostate cancers, in addition to both fusion positive and fusion negative rhabdomyosarcoma." (PMID 36831514, 2023). "Alteration of FGFR4 signaling is a common mechanism of oncogenesis in both fusion positive and fusion negative rhabdomyosarcoma (RMS)." (PMID 24124571, 2013). "Chimeric antigen receptor (CAR) T-cells targeting Fibroblast Growth Factor Receptor 4 (FGFR4), a highly expressed surface tyrosine receptor in rhabdomyosarcoma (RMS), are already in the clinical phase of development, but tumour heterogeneity and suboptimal activation might hamper their potency." (PMID 39043633, 2024). "Similar to PD-1-blocking antibodies, the blockade of PD-L1 could have beneficial effects in the combination with CAR-T cells, as demonstrated by the successful eradication of rhabdomyosarcoma in an orthotopic murine model by novel FGF receptor 4 (FGFR4, CD334)–specific CAR-T cells." (PMID 36768665, 2023). "It is confirmed that kinase inhibitor treatment increased cell apoptosis in FGFR4-mutant rhabdomyosarcoma (RMS) cell lines, which is consistent with increased SubG1 fraction and high level of activated caspase-3, suggesting the strong dependency of RMS on FGFR4." (PMID 35494629, 2022). "Moreover, PTPRG could also modulate the activity of FGFR4 in rhabdomyosarcoma, indeed using siRNA against PTPRG in FGF-treated RH30 cell line increases phosphorylation of the receptor FGFR4 and downstream molecule such as PLCG1 (Phospholipase C-gamma 1) compared to the scramble control." (PMID 35071225, 2021).
colorectal cancer (34 papers, 2013 to 2026). A primary or metastatic malignant neoplasm that affects the colon or rectum. "Tumor-associated fibroblast (TAF)-derived CCL2 and downstream transcription factor Ets-1 are associated with TAF-induced fibroblast growth factor receptor 4 (FGFR4) upregulation in colorectal cancer cell lines." (PMID 40777019, 2025). "The aim of this study was to associate FGFR4 rs1966265 and rs351855 variants with colorectal cancer (CRC) in a Mexican population and to perform in silico analysis." (PMID 38540215, 2024). "For example, increased FGFR2 and FGFR4 expression were associated with poor response to neoadjuvant chemoradiation in colorectal cancer patients." (PMID 31948066, 2020). "Previously, we demonstrated that autoantibodies directed against FGFR4, in combination with other tumor-associated antigens (TAAs), can be used as early diagnostic markers of colorectal cancer." (PMID 23696849, 2013). "Here, FGFR4 mutation analysis discarded the presence of activating mutations, other than Arg388, in different colorectal cancer cell lines and tumoral samples." (PMID 23696849, 2013). "We investigated FGFR4 mutations in colorectal cancer cell lines and cancer samples that could contribute to antibody recognition by overexpression or activation." (PMID 23696849, 2013). "FGFR4 mutational status in colorectal cancer and control cell lines." (PMID 23696849, 2013). "However, loss-of-function experiments revealed a major role of FGFR4 in tumorigenic properties of colorectal cancer cells, since its depletion abrogated proliferation, adhesion, migration and invasion." (PMID 23696849, 2013). "In addition, we observed a clear overexpression of FGFR4 in colorectal cancer cell lines (particularly in 2 out of 4 highly metastatic colorectal cancer cell lines) with a potential association of FGFR4-expression to late stages colorectal cancer." (PMID 23696849, 2013). "We have used different colon cancer samples and cell lines (SW480, SW620, SW48, KM12C and KM12SM) to investigate the presence of SNPs or activating mutations in FGFR4 and to characterize its biological relevance as oncogene and therapeutic target in colorectal cancer." (PMID 23696849, 2013). "Interestingly, FGFR4 p.Gly388Arg was found to be correlated with worse outcomes in breast and lung cancer, and very recently, in silico analysis in a Mexican population with colorectal cancer showed an association between rs351855 and the disease." (PMID 38650006, 2024). "FGFR4 expression was assessed across colorectal cancer cell lines representing various molecular subtypes." (PMID 41210688, 2025). "Western blot analysis confirmed the increased expression of IFN-β and CXCL10 as well as phosphorylation of TBK1, IRFs, and STAT1 in FGFR4-overexpressing colorectal cancer cells." (PMID 40447617, 2025). "RT-qPCR analysis revealed significantly higher levels of FGFR4 in colorectal cancer cells compared to normal intestinal epithelial cells (NCM460)." (PMID 41210688, 2025). "This unique structure enables a specific FGFR4 inhibitor, which can be promising in cancers that have overexpressed FGFR4, such as colorectal cancer." (PMID 39796710, 2024). "Prior reports showed that FGFR4 is highly expressed in many different cancers, such as lung cancer, colorectal cancer, liver cancer, esophageal cancer, gastric cancer, and ovarian cancer." (PMID 35513870, 2022). "In human colorectal cancer, fibroblast growth factor receptor 4 (FGFR4) is usually upregulated as an oncogene." (PMID 30112378, 2018). "Regarding the expression of FGFR4 in colorectal cancer cells, an overexpression of FGFR4 at protein level in 10 out of 11 CRC cells in comparison to control cells was reported, with a larger expression of FGFR4 in highly metastatic CRC cells." (PMID 28376106, 2017). "FGFR4 protein overexpression was shown to be an independent prognostic factor in non-small cell lung cancer and colorectal cancer." (PMID 28056982, 2017).